PARK7 (Parkinsonism associated deglycase)
Diseases named in the same sentence as PARK7 in open-access papers (continued):
Sharing a sentence is not in itself a finding about the gene and the disease.
Stroke (34 papers, 2011 to 2025). Sudden impairment of blood flow to a part of the brain due to occlusion or rupture of an artery to the brain. "PARK7/DJ-1-deficient animals produced a significantly larger infarct size in the animal model of Endothelin-1 induced stroke compared to wild-type controls." (PMID 35743072, 2022). "However, the abnormal function of LRRK2, GBA, SNCA, PARK2, PARK6, and PARK7 genes has been linked to alteration in innate and adaptive immune responses in cancer, stroke, diabetes, male infertility, Crohn's disease, and infectious diseases." (PMID 34239490, 2021). "Finally, they concluded that even though both markers cannot differentiate stroke etiologies (ischemic or hemorrhagic), plasma PARK7 has better diagnostic value than NDKA for early diagnosis of stroke." (PMID 31827893, 2019). "Additionally, Park7, Prdx6, and Jun in plasma EVs might serve as markers of pathological processes associated with stroke." (PMID 41164797, 2025). "A subsequent study demonstrated that NDKA and PARK7 were significantly increased in stroke patients compared to controls (p < 0.0001), for NDKA the sensitivity and specificity were 90%." (PMID 39001884, 2024). "NDKA and PARK7 can be considered to be acute stage markers, as they can be detected within three hours after stroke." (PMID 39001884, 2024). "A study has shown that PARK7 and NDKA are increased at 3 h after stroke with a sensitivity of 54–91% for PARK7 and 70–90% for NDKA and specificity of 80–97% for PARK7 and 90–97% for NDKA." (PMID 37511304, 2023). "In this study, we examined the association between serum NDKA, NMDA, PARK7, and UFDP levels and the phlegm-heat syndromes of acute ischemic stroke and explored their value in evaluating the clinical efficacy of stroke." (PMID 26539220, 2015). "NDKA and PARK7 concentrations were slightly reduced in late stroke patients (NDKA in early patients mean (ug/L) ± SD: 24.0±57.3; late patients mean± SD: 13.5±28.8; PARK7 early patients mean (ug/L) ± SD: 215.3±313.5; late patients mean± SD: 147.0±366.9)." (PMID 23028472, 2012). "Ubiquitin fusion degradation protein-1 (UFD-1), along with PARK7 and NDKA, were first detected in post-mortem CSF samples of stroke patients, and subsequently confirmed as early plasma markers of stroke." (PMID 39001884, 2024). "The serum NDKA, NMDA, PARK7, and UFDP levels; NIHSS scores; and phlegm-heat syndrome scores were measured within 3 days of onset and at 7 days and 14 days after the onset of stroke in 51 acute ischemic stroke patients." (PMID 26539220, 2015). "This study found that serum PARK7 and UFDP levels in stroke patients with phlegm-heat syndrome within 3 days of onset were statistically different from the healthy subjects." (PMID 26539220, 2015). "Previous studies have revealed that NDKA, NMDA, PARK7, and UFDP levels were significantly elevated in stroke patients within 3 h of onset and had certain sensitivity and specificity in the diagnosis of ischemic stroke." (PMID 26539220, 2015). "However, currently, there were no reports on the associations between serum PARK7 and UFDP levels and other diseases such as coronary heart diseases and hypertension as well as stroke patients without phlegm-heat syndrome." (PMID 26539220, 2015). "Therefore, serum PARK7 and UFDP levels could not be used as a marker for the diagnosis of stroke with phlegm-heat syndrome currently." (PMID 26539220, 2015).
Alzheimer disease (26 papers, 2009 to 2025). A progressive, neurodegenerative disease characterized by loss of function and death of nerve cells in several areas of the brain leading to loss of cognitive function such as memory and language. "Importantly, we detected 25 HLA epitopes derived from 15 genes associated with Alzheimer’s and related dementias such as Tau, PLD3 (Alzheimer’s disease), TDP-43, FUS (Frontotemporal dementia), and PARK7, VPS35 (Lewy Body dementia)." (PMID 40568088, 2025).
melanoma (25 papers, 2014 to 2025). A malignant, usually aggressive tumor composed of atypical, neoplastic melanocytes. "PARK7, associated with early-onset PD, is significantly upregulated in melanoma, inhibiting apoptosis." (PMID 40860809, 2025). "PARK2, PARK5, and PARK7 expression promotes melanoma proliferation and migration, which are negatively correlated with PD." (PMID 40860809, 2025). "Increased expression of DJ-1, encoded by PARK7, has been observed in melanomas and breast, lung, colorectal, uterine, hepatocellular, and nasopharyngeal cancers." (PMID 37481603, 2023). "Loss of heterozygosity of PARK2, LRRK2 mutations causing neuronal cell death and neurotoxicity, BRAF kinase alterations, and PARK7 oncogene activation with subsequent melanoma development are possible underpinning genetic pathophysiologiy." (PMID 35247252, 2022). "PARK1, PARK2, PARK5, and PARK7 are usually overexpressed in melanoma." (PMID 40860809, 2025). "For PARK7, a significantly higher expression was observed in primary melanomas (p = 0.00272)." (PMID 38189631, 2024). "Furthermore, the interaction between PARK7 and α-syn, although not well understood, may synergistically promote melanoma cell proliferation, given their elevated expression in melanoma." (PMID 40860809, 2025). "We observed that ENO1, PARK7, NPM1 and STMN1 genes expression levels were higher in melanoma cells than in melanocytes and in normal fibroblasts." (PMID 29545914, 2018). "In melanoma cell lines, PARK7 expression is positively correlated with migratory ability, and patients with metastatic uveal melanoma had significantly higher levels of serum DJ-1 (Chen L.-L." (PMID 32210791, 2020). "In addition, a good positive correlation (spearman's test) between SNCA and PARK7 expression was observed in primary melanomas (ρ = 0.48, p = 0.00019), but not in benign melanocytic nevi (ρ = 0.34, p = 0.12)." (PMID 38189631, 2024). "Unlike its antioxidant function in PD, PARK7 downregulates the PTEN-regulated PI3K/AKT pathway, thereby regulating melanoma cell proliferation." (PMID 40860809, 2025).
diabetes (23 papers, 2012 to 2025). "Our previous study found that the infarct-limiting effect of IPostC is abolished in the heart of diabetes whose cardiac expression of DJ-1 (also called PARK7, Parkinsonism associated deglycase) is reduced." (PMID 38698453, 2024). "In the group enriched with diabetic patients (6 out of 9 patients), seven proteasome genes (PSME4, PSMA7, PSMB4, PSMB6, PSMC4, PSMD7 and PSMD8) and three genes previously associated with common diabetes (SNX17, PARK7/DJ-1 and ATP5B) were highly expressed." (PMID 32302349, 2020). "Specifically, succination of critical cysteine in GAPDH, GMPR and PARK7/DJ-1 were found in mice lacking Fh1 that develop progressive glucose intolerance and diabetes at around week 6–8 after birth." (PMID 31900386, 2020).
hepatocellular carcinoma (23 papers, 2012 to 2025). A malignant tumor that arises from hepatocytes. "WTAP suppression attenuates circCMTM3 m6A modification, thereby promoting ferroptosis in hepatocellular carcinoma, while circCMTM3 silencing destabilizes parkinsonism-associated deglycase (PARK7) via IGF2BP1 binding to induce ferroptosis." (PMID 40986143, 2025). "Additionally, Parkinsonism-associated deglycase (DJ-1), known to be upregulated in hepatocellular carcinoma (HCC), was also detected." (PMID 38590903, 2024). "The m6A writer WTAP-mediated m6A modification on circCMTM3 inhibits hepatocellular carcinoma ferroptosis by recruiting IGF2BP1 to increase the stability of Parkinson’s protein 7 (PARK7)." (PMID 37714846, 2023). "Indeed, it was recently demonstrated that the miR-128-3p directly reduces the expression of PARK7/DJ-1 in hepatocellular carcinoma cells by binding to the 3′UTR region of PARK7/DJ-1." (PMID 35743072, 2022). "PARK7 has been identified as a critical regulator of tumor progression in hepatocellular carcinoma (HCC)." (PMID 32357493, 2020). "Although PARK7 has been found modulated in several pathological conditions, such as endometriosis and hepatocellular carcinoma, our results, supported by two techniques, show that PARK7 is not differentially expressed in obesity." (PMID 22272336, 2012).
pancreatic cancer (19 papers, 2008 to 2025). "In some cancers, such as endometrial cancer, non-small cell lung cancer, pancreatic cancer, esophageal squamous cell carcinoma, and cervical cancer, high expression of PARK7 is significantly associated with metastasis or worse prognosis." (PMID 39276379, 2024). "The serum levels of PARK7 serve as a potential diagnostic and prognostic biomarker in pancreatic cancer." (PMID 32357493, 2020). "The serum levels of PARK7 are significantly increased in patients with pancreatic cancer compared to those in healthy tissues, and this elevation is associated with tumor differentiation and reduced survival of patients with pancreatic cancer." (PMID 32357493, 2020). "The upregulation of PARK7 enhances tumor formation and the metastasis of pancreatic cancer and disrupts the extracellular matrix of the cancer cells by inducing the expression of the urokinase plasminogen activator by activating Src and ERK." (PMID 32357493, 2020). "In addition, the elevated PARK7/DJ-1 expression was closely correlated with the poor survival of patients with colorectal and pancreas cancers." (PMID 35743072, 2022). "As an example, one of the up-regulated spots was the oncoprotein DJ-1 (PARK7), which transforms mouse 3T3 cells in vitro and is also elevated in many non-virally induced human cancers, including lung, breast, ovarian, thyroid, and pancreatic cancers." (PMID 19698150, 2009). "Similarly, miR-203 was shown to reduce PARK7/DJ-1 expression in pancreatic cancer cells." (PMID 35743072, 2022). "Among the upregulated proteins in the exosomes of patients with pancreatic cancer, exostosin-like glycosyltransferase 2 (EXTL2), α-2-macroglobulin like 1 (A2ML1), and Parkinson's disease protein 7 (PARK7) were the most significantly overexpressed." (PMID 40331617, 2025). "The expression of miR-142 is also significantly reduced in patients with pancreatic cancer, and this inhibits the expression of HIF1A and PARK7, which enhances the sensitivity of the pancreatic cancer cells to adriamycin." (PMID 32357493, 2020). "The miR-203 miRNA reduces the proliferation and cisplatin resistance of pancreatic cancer cells by inducing the expression of PTEN and suppressing the activation of PARK7 and AKT." (PMID 32357493, 2020). "Also, in accordance with our results, PARK7 was found to be significantly elevated in PDAC, correlated with tumor invasion and worse patients’ outcome, and responsible for promoting invasion and metastasis of pancreatic cancer cells." (PMID 32197468, 2020).
colorectal cancer (18 papers, 2011 to 2025). A primary or metastatic malignant neoplasm that affects the colon or rectum. "Colorectal cancer cells treated with ciclopirox olamine (CPX) was similarly found to downregulate Parkinsonism associated deglycase (PARK7, DJ-1), which increased ROS production and mitochondrial dysfunction to induce mitophagy in a pro-survival manner." (PMID 34069611, 2021). "In malignant diseases, the increased expression of PARK7/DJ-1 was demonstrated in glioblastoma, non-small cell lung, thyroid, breast, hepatocellular, and colorectal carcinoma." (PMID 35743072, 2022). "Proteomic analysis revealed that the levels of PARK7 are increased in several types of cancer, and O-acetylglucosamine (GlcNAc)-modified PARK7 is involved in the pathogenesis of colorectal cancer (CRC) and human scirrhous-type gastric carcinoma (GC)." (PMID 32357493, 2020). "The PARK7 expression in colorectal cancer tissues was higher than that in normal colon tissues and PARK7 downregulated the tumor suppressor PTEN." (PMID 31240215, 2019). "Recent studies have also confirmed that PARK7 promotes the proliferation and metastasis of colorectal cancer by activating the Hh and Wnt signaling pathways, and that PARK7 increases proteins involved in the Hh signaling pathway, including GLI1, GLI2, and PTCH1." (PMID 39276379, 2024). "Our previous studies showed that PARK6 (PINK1) can promote migration and proliferation of lung cancer cells by regulating autophagy, and PARK7 (DJ-1) is necessary for the transcription of HIF-1α and survival of colorectal cancer cells." (PMID 34616772, 2021).
lung cancer (16 papers, 2006 to 2025). A malignant neoplasm involving the lung. "The nuclear expression of PARK7 stabilizes nuclear factor erythroid 2-related factor (Nrf2) in lung cancer tissues and is significantly associated with the cytoplasmic stability of Nrf2." (PMID 32357493, 2020). "Another study demonstrated that PARK7 is highly expressed in patients with lung cancer, and its elevated expression is associated with the poor survival and relapse of lung cancer." (PMID 32357493, 2020). "α-1-microglobulin/bikunin precursor (AMBP), peroxiredoxin 2 (PRDX2), and Parkinson’s disease protein 7 (PARK7) are three protein markers associated with lung cancers." (PMID 29597315, 2018). "Here, we present a novel suspension microarray for multiplexed analysis of three protein markers associated with lung cancer: α-1-microglobulin/bikunin precursor (AMBP), peroxiredoxin 2 (PRDX2), and Parkinson disease protein 7 (PARK7)." (PMID 28300171, 2017). "Higher concentrations of AMBP and PRDX2 markers were found in the lung cancer group compared to the control group (with a fold change (FC) of 3.4 and 2.0, respectively), whereas PARK7 concentration was lower (FC = 0.49)." (PMID 28300171, 2017). "The statistical results of the preclinical validation of the QDEM and xMAP® 3-plex immunoassays detecting AMBP, PRDX2, and PARK7 markers as tools for diagnosis of lung cancer were practically identical." (PMID 28300171, 2017). "In order to compare QDEM and xMAP® technologies, the same 3-plex immunoassay for the quantification of AMBP, PRDX2, and PARK7 lung cancer markers was developed for xMAP®." (PMID 28300171, 2017). "As in the QDEM-based analysis, the concentrations of AMBP and PRDX2 markers in the lung cancer group were found to be higher than in the control group (FCs of 5.30 and 2.62, respectively), whereas PARK7 concentration was lower (FC = 0.36)." (PMID 28300171, 2017).
ovarian carcinoma (16 papers, 2012 to 2025). A malignant neoplasm originating from the surface ovarian epithelium. "Furthermore, IGF2BP1 can promote ferroptosis resistance by stabilizing ferritin heavy chain 1 (FTH1), signal transducer and activator of transcription 3 (STAT3), and parkinsonism-associated deglycase (PARK7) mRNAs in HCC, bladder cancer, ovarian cancer, and GC, respectively." (PMID 40584294, 2025). "The elevated expression of PARK7 is significantly associated with the stage, grade, and poor progression-free survival of ovarian tumors, and is highly expressed along with phospho-AKT and mTOR in patients with ovarian cancer and peritoneal malignant effusions." (PMID 32357493, 2020). "Lovastatin, which possesses cholesterol-lowering and potential antineoplastic activities, induces apoptosis in ovarian cancer cells by inducing PTEN and reducing phosphor-AKT via inhibition of PARK7 expression." (PMID 32357493, 2020). "The remaining three proteins (CXCL13, PARK7, and LAP.TGF-β1) do not appear in the literature as having an association with ovarian cancer, however they have been identified in other types of cancer." (PMID 29051715, 2017).
Sepsis (15 papers, 2016 to 2025). Sepsis is defined as life-threatening organ dysfunction caused by a dysregulated host response to infection. "The deficiency of PARK7 was found to impact the gut microbiota and impair bacterial clearance in sepsis, suggesting it may have a role in shaping the homeostasis of the microbial community." (PMID 38622589, 2024). "Recent studies indicated that restoration of Park7 expression rescues ROS production and improves survival in LPS-induced sepsis." (PMID 27389701, 2016). "For research on sepsis in the late stage, Park7 KO mice can be an ideal model." (PMID 30542343, 2018). "AXL, CDH16, PARK7, and PGLYRP2 were significantly changed in the urine of patients suffering from sepsis-induced AKI." (PMID 32194432, 2020). "ROC curve analysis revealed that proteins (PARK7 and CDH16) could accurately discern sepsis-induced AKI patients, with the AUCs being 0.900 and 0.898, respectively." (PMID 32194432, 2020). "Therefore, PARK7 and CDH16 were confirmed to be novel biomarkers after validation in sepsis human patients." (PMID 32194432, 2020). "The interaction of Park7 and p47phox can activate NADPH oxidase and subsequently increase ROS in macrophages to initiate TRL signaling to in turn, reinforce macrophage functions to protect against sepsis–induced immunosuppression." (PMID 30542343, 2018). "PARK7 and CDH16 could accurately discern sepsis-induced AKI patients with high AUC." (PMID 32194432, 2020).
Obesity (14 papers, 2012 to 2025). Accumulation of substantial excess body fat. "Mice with Park7 deficiency showed resistance to high‐fat diet (HFD)‐induced obesity by enhancing energy expenditure." (PMID 36149763, 2022). "Accordingly, EVs from hypertrophied and IR adipocytes, showed to transport proteins previously associated to obesity and to IR such as calreticulin, S100A6, mimecan, PARK7/DJ1, PPIB, and tenascin." (PMID 33316953, 2020). "ENOA, PARK7 and Beta-actin are proper reference standards in obesity studies based on omental fat, whilst FAA is the best loading control for the comparative analysis of omental and subcutaneous adipose tissues either in obese and non-obese subjects." (PMID 22272336, 2012). "Animal studies have shown that raised PARK7 is correlated with obesity." (PMID 38703299, 2024). "In addition, some other proteomics studies in obesity suggests that PARK7 are a proper reference standard in obesity studies based on VAT." (PMID 38703299, 2024). "Elevated in vesicles from oleic acid hypertrophied adipocytes are other proteins of interest in relation to adipose tissue and obesity, such as PARK7/DJ-1 and MMP-14." (PMID 32214011, 2020). "PARK7 protein abundance was found increased on SAT and SKM of individuals with obesity." (PMID 38703299, 2024). "Accordingly, only ENOA, PARK7 and β-actin proteins were reported as proper reference standards for omental fat in obesity studies, while FAA was shown to be the best control for both omental and subcutaneous adipose tissues regardless of the obesity status." (PMID 24086512, 2013).
Onset (14 papers, 2011 to 2023). The age group in which disease manifestations appear. "PARK7, responsible for encoding the DJ-1 protein, is another gene that plays a significant role in autosomal recessive early-onset PD and has garnered attention concerning microglial function and neuroinflammation." (PMID 38069088, 2023). "Mutations in the PARK7 locus, which encodes the DJ-1 protein, cause autosomal recessive, early-onset Parkinson’s disease and oxidized DJ-1 has been observed in brains of idiopathic PD patients." (PMID 36151217, 2022). "Loss-of-function mutations in DJ-1 (PARK7) are associated with autosomal recessive early onset PD." (PMID 34827436, 2021). "Defects in the gene encoding DJ-1 protein cause an autosomal recessive early-onset PD, PARK7." (PMID 25426023, 2014). "DJ-1 belongs to the peptidase C56 protein family and is encoded by the PARK7 gene, whose mutations have been associated with autosomal recessive early onset PD." (PMID 33800548, 2021). "PARK2, PARK7, and PINK1 are known to cause early-onset PD with a recessive inheritance mode, while SNCA and LRRK2 are known to cause dominantly inherited PD." (PMID 30917570, 2019).